CLDN4 (claudin 4)
Diseases named in the same sentence as CLDN4 in open-access papers (continued):
Sharing a sentence is not in itself a finding about the gene and the disease.
cancer (continued). "Other claudin family members besides CLDN1, CLDN3, CLDN4, CLDN6 and CLDN18.2 have also been implicated in various stages of cancer progression, including metastasis." (PMID 38371623, 2024). "Conjugation of CPE and anti-cancer drugs produces a carrier for targeted delivery to cancer cells expressing CLDN4." (PMID 38731853, 2024). "Our findings suggested that CLDN4 was intimately connected to the invasion of immune cells and possesses significant potential as a therapeutic target in the treatment of cancer." (PMID 37057131, 2023). "The overexpression of CLDN4 in many cancers has drawn attention to this protein as a new molecular target." (PMID 36982569, 2023). "This suggest that increases CLDN4 level and functional activity can inhibit the progression of cancer." (PMID 36959784, 2023). "CMS3 cancers with KRAS mutations presented a slight upregulation of claudin 4, while CMS3 cancers with wild-type KRAS displayed suppressed expression of claudin 4 (two-tailed t test p < 0.05, left)." (PMID 37998722, 2023). "Claudin-4 (CLDN4), a tight junction protein, is overexpressed in several types of cancer, and is considered a biomarker for cancer-targeted treatment." (PMID 37237291, 2023). "Changes in DNA methylation, histone modifications, chromatin remodeling, and microRNAs are considered useful indicators of cancer development and progression, and epigenetic changes in the regulation of CLDN4 expression have recently been reported." (PMID 36982569, 2023). "Using a pancancer investigation, we discovered that multiple different types of tumors had a dysregulated level of CLDN4, which suggests that this gene plays a significant role in the progression of cancers." (PMID 37057131, 2023). "Dox (red) was localized in the nucleus (blue) of ASPC-1 and KPC960 cells, indicating that D@C-LPs were taken up by CLDN4-positive cancer cells and subsequently released Dox intracellularly." (PMID 37237291, 2023). "Multiple research over the past few years have pointed to an essential function for CLDN4 in the development of various distinct types of cancer." (PMID 37057131, 2023). "Abnormal CLDN4 expression reduces the stability of cell–cell adhesion and promotes cancer development." (PMID 38201579, 2023). "The authors also discovered that lower-grade carcinomas exhibit higher claudin-4 expression compared to higher-grade carcinomas, with epithelial cells in benign glands surrounding the cancer sections displaying moderate to strong claudin-4 staining." (PMID 38188015, 2023). "As expected, the cytotoxicity of D@C-LPs towards cancer cells varied according to the expression of CLDN4, with more severe cytotoxicity observed in CLDN4-positive ASPC-1 and KPC960 cells compared with CLDN4-negative A549 cells." (PMID 37237291, 2023). "In recent years, a number of studies have indicated that an improper control of CLDN4 played a role in the evolution of a number of different cancers." (PMID 37057131, 2023). "Targeting of CLDN4 is expected to provide multi-layered effects by enabling direct attacks on CLDN4-overexpressing cancer cells, disrupting the intratumoral microenvironment, and facilitating drug delivery by impairing TJs." (PMID 36982569, 2023). "CLDN4 is also overexpressed in thyroid cancer and prostate cancer; however, in these cancers, decreased expression correlated with poor prognosis." (PMID 36982569, 2023). "Dox-loaded C-LPs (D@C-LPs) specifically delivered Dox to CLDN4-expressing cancer cells, effectively inducing cytotoxicity." (PMID 37237291, 2023). "For example, Pseudomonas aeruginosa exotoxin A, diphtheria toxin fragment A, doxorubicin-loaded polysialic acid nanoparticles, 111In, TNF, and nanomaterials such as gold nanoparticles bound to C-CPE induces cell death in CLDN4-expressing cancer cells." (PMID 36982569, 2023). "Several studies have suggested that CLDN4 expression is involved in promoting cancer cell viability." (PMID 36982569, 2023).
cancer (continued). "Maintenance of the intratumor microenvironment by CLDN4 promotes malignant phenotypes in cancer through retention of growth factors and suppression of oxidative stress." (PMID 35742959, 2022). "TGF-β and SMAD2/3/4 signaling regulate CLDN4 promoter activity, and expression levels differ between cancers." (PMID 36620607, 2022). "Our findings support the value of high CLDN-4 expression as an auxiliary marker for the prediction of synchronous tumors as well as early cancer generation." (PMID 35743616, 2022). "Here, we analyzed 157 cases of BUC and investigated the hypomethylation of CpG island in the CLDN4 promoter DNA and its correlation with cancer progression." (PMID 35742959, 2022). "In two of them (patient 6 and 8), the strong Claudin-4 staining was in favor of a carcinoma diagnosis." (PMID 35864317, 2022). "Although KRTAP5-AS1 has not been associated with PCa, it has recently shown that it can act as a miRNA sponge for miRNAs such as mir-596, which targets CLDN4, an oncogene enhancing the invasion capacity of cancer cells promoting EMT." (PMID 34311724, 2021). "We also detected enrichment for transcripts encoding fibroblast-specific protein 1 (FSP1/S100a4), keratins Krt7, Krt8, Krt14 and Krt18 and claudins Cldn3, Cldn4 and Cldn7 in this cluster which were also enriched in epithelial/cancer cells." (PMID 32455670, 2020). "We previously reported that CPE produced by C. perfringens impairs CLDN4, which forms tight junctions, to promote cancer progression by activating YAP." (PMID 32485921, 2020). "Cancer progression was compared between the cases in which nuclear CLDN4 was observed (including cases with positive expression in the nucleus and cytoplasm) and the cases in which CLDN4 expression was found in the cell membrane." (PMID 32064037, 2020). "CLDN4 expression was diffusely observed in the nuclei of cancer cells in 5 out of 202 cases, all of which were pT3." (PMID 33172177, 2020). "In this study, OSCCs showing nuclear CLDN4 expression were found more strongly correlated with cancer progression than those showing cell membrane CLDN4 expression." (PMID 32064037, 2020). "Claudin-4 overexpression is a common signature of this process and is considered a promising biomarker for cancer detection and prognosis in a variety of cancer types." (PMID 32414951, 2020). "According to many studies CLDN4 is overexpressed in many epithelial malignancies and it has been correlated with cancer progression." (PMID 32064037, 2020). "For cases wherein CLDN4 expression was observed in the nucleus, the cancer was significantly advanced." (PMID 33172177, 2020). "The specificity for carcinoma detection was 93.93, 81.81 and 96.96% for claudin-4, MOC-31 and p16, respectively." (PMID 32178642, 2020). "CPE is regarded as a therapeutic tool for epithelial malignant tumors by utilizing the damage of CLDN4 and CLDN3." (PMID 32064037, 2020). "Surprisingly, only two genes appeared in both the “epithelial targets” and “cancer targets” tables—Tmem54 and Claudin-4, a previously experimentally validated Grhl-target." (PMID 31683705, 2019). "The binding ability of CPE to claudins, especially claudin-3 and claudin-4, has raised a great opportunity to target cancers with dysregulated claudin-3 and -4 cancers, especially breast, ovarian, and pancreatic cancers." (PMID 31861759, 2019). "The dual-targeting antibodies against CLDN3 and CLDN4 have shown anti-cancer efficacy in a preventive model in which the antibody was injected on day 0 after the inoculation of cancer cells." (PMID 31905631, 2019). "Taken together, these results highlight the utility of claudin-4 overexpression not only as an early detection marker for many different cancers, but also as a cancer type-specific prognostic indicator." (PMID 28842811, 2018). "Here we describe the impact of several parameters on antigen expression and the development of mAbs against human claudin 4 (CLDN4), a potential multi-indication cancer target." (PMID 29856790, 2018).
cancer (continued). "Here we sought to develop a panel of mAbs against an emerging cancer target, human claudin 4 (CLDN4)." (PMID 29856790, 2018). "With 76.92% of patients showing higher expression in cancer tissue, the transcriptional level of CLDN4 was significantly higher in the GC tissues compared with matched non-tumorous adjacent tissues via Wilcoxon’s Sign Rank Test (P < 0.001)." (PMID 28819095, 2017). "Claudin 4 is thus a potent target for cancer therapy, and that an anti-Claudin 4 antibody is a promising candidate anticancer agent." (PMID 28376864, 2017). "Among the results of the analysis for potential mRNA–ceRNA interactions in the “Tight junction” pathway, CLDN4 goaded our interest since it is closely related to cancer development." (PMID 28819095, 2017). "Given the significant effects of CLDN4 on cancer metastasis, as revealed by our work and others, the regulatory network related to CLDN4 urgently needed to be explored." (PMID 28819095, 2017). "Although there have been several studies focusing on investigating the expression profile and function of CLDN4 in different cancers, the upstream regulatory mechanism of CLDN4 has rarely been explored until now." (PMID 28819095, 2017). "In situ hybridization (ISH) results in 20 cases of GC showed that CLDN4, miR-596, and miR-3620-3p were expressed by epithelial and carcinoma cells and mainly localized in the cytoplasm." (PMID 28819095, 2017). "It is therefore somewhat paradoxical that claudin-4 is highly expressed in many types of epithelial tumors including ovarian, breast, gastric, hepatic, pancreatic and other cancers of epithelial origin." (PMID 27724921, 2016). "In both the primary cancers and the metastases, Claudin-4 was most frequently expressed, followed by GLUT-1, CAIX, EGFR and IGF1R." (PMID 25417118, 2014). "Additional studies have been warranted to investigate the correlation between claudin-4 overexpression and cell invasion in various cancer cells." (PMID 25120725, 2014). "In both the primary cancers and the metastases, Claudin-4 was most frequently expressed, followed by GLUT-1, CAIX and EGFR." (PMID 25417118, 2014). "Tight junction molecules, such as CLDN1, improved invasion activity in cancer cell lines through activation of MT1-MMP-1 and MMP-2, and peak expression of claudin-4 RNA has been temporally associated with the implantation window in humans." (PMID 24564230, 2014). "In the current study, claudin-4 was immunopositive in regions of dysplasia and/or carcinoma in all cases." (PMID 24765156, 2014). "Claudin-4 has been shown to activate MMP-2 and claudin-4 expression has been significantly associated with MMP-9 expression, indicating that claudin-mediated increased cancer cell invasion result from activation of MMP proteins." (PMID 23919729, 2013). "Abnormal expression of claudin molecules, such as claudin-4, by neoplastic cells is possibly an important determinant of local invasion and dissemination and claudin represents a promising target for cancer detection, diagnosis and therapy." (PMID 23599806, 2013). "Taking advantage of the fact that CLDN-4 is overexpressed on a range of cancer cells, we thus constructed a cDNA comprising C-CPE and a fragment of exotoxin A(ETA') (C-CPE-ETA')." (PMID 22737166, 2012). "Cancer patients that demonstrated high levels of CA125 also tended to exhibit high levels of claudin-4." (PMID 19619303, 2009). "The tight junction protein claudin 4 (CLDN4) is also frequently overexpressed in several cancers, and is thought to represent a promising target for cancer detection, diagnosis, and therapy." (PMID 18827820, 2008). "Some of the tight junction proteins including Claudin-1 and Claudin-4 are upregulated in several cancers." (PMID 18781153, 2008). "Of 179 HEG1-positive carcinomas, 172 expressed the epithelial marker claudin-4." (PMID 41656400, 2026).
cancer (continued). "The correlation heat map of CLDNs expression in pan-cancer showed that the expression of most CLDNs was positively correlated, among which CLDN4 and 7 had the highest correlation coefficient of 0.89, indicating that CLDNs has a certain combined application value in tumors." (PMID 41461671, 2025). "For developing new treatment options in brain metastasis from BC, Clostridium perfringens enterotoxin (CPE) in interaction with claudin-4, used as a possible biomarker for BC, can induce disruption of cancer cell membrane permeability and an influx of calcium ions, followed by cancer cell death." (PMID 40149641, 2025). "Monoclonal antibodies targeting CLDNs, particularly CLDN1 and CLDN4, hold promise as therapeutic agents in the treatment of various cancers, with potential synergistic effects when combined with known anti-cancer agents like 5-fluorouracil and anti-EGFR antibodies." (PMID 38731853, 2024). "Moreover, we introduced Claudin‐4 (CLDN4), a gene that expressed on cancer cells, had the potential to be the predictive biomarker of recurrent MPE among advanced NSCLC patients." (PMID 38629624, 2024). "Although mild expressions were demonstrated in total cancer cell cluster C1 and C8 in non‐recurrent group, the CLDN4 expression along with ELF3, TACSTD2 and EpCAM could only be seen in recurrent cells of total C1." (PMID 38629624, 2024). "Epithelial-mesenchymal transition may be mediated by overexpression of CLDN4, is considered a risk factor for KIRC, for its aiding cancer metastasis." (PMID 39440053, 2024). "Clusters of TCF4 binding sites are present in promoters of the CLDN2, CLDN4, CLDN7, and OCLN genes, and these genes could thus be upregulated in cancers with APC mutations." (PMID 37998722, 2023). "CLDN4 is overexpressed in many epithelial malignancies and correlates with cancer progression." (PMID 36982569, 2023). "There have been a number of attempts to target CLDN4 for cancer therapy." (PMID 36982569, 2023). "Furthermore, by conjugating toxins and anticancer drugs to C-CPE, it becomes a carrier that delivers these to cancer cells expressing CLDN4." (PMID 36982569, 2023). "CLDN4 expression is correlated to cancer progression in these cancers." (PMID 35742959, 2022). "In our previous study, CLDN4 overexpression correlated with cancer progression in BUC." (PMID 35742959, 2022). "CLDN4 has been reported to be frequently upregulated in variety of cancers." (PMID 35418179, 2022). "It has been shown that zinc finger protein 703 may be a promising target for cancer therapy by directly binding to and transfecting the CLDN4 promoter to activate the expression of CLDN4, inducing EMT and inhibiting the sensitivity of HCC cells to sorafenib." (PMID 34367979, 2021). "Claudin-4 appears to be elevated at the protein level in a variety of human carcinomas." (PMID 34638619, 2021). "Accumulating evidencehas indicated that abnormal expression of CLDN4 may lead to a tendency for cancer to metastasizemainly because CLDN4 could significantly increase cancer cells invasive properties and promote epithelial-mesenchymal transition (EMT)." (PMID 32269215, 2020). "Hence, claudin-4 can be regarded not only as a promising biomarker for early detection of PDAC but also as a cancer type–specific prognostic indicator." (PMID 32414951, 2020). "The effects of nuclear CLDN4 on cancer cells by CPE treatment were also examined." (PMID 32064037, 2020). "However, employment of wild‐type CPE (CPEwt) for cancer treatment is restricted to carcinomas, which express CPEwt‐binding claudins (e.g., Cldn3, Cldn4)." (PMID 31825142, 2020). "Furthermore, comparison between the expression of biglycan and Claudin-4 in cancer cells showed that the expression of Claudin-4 was significantly decreased in biglycan (+) cases." (PMID 32821344, 2020). "As a member of the CLDNs family, CLDN4 has been shown to participate in cancer development." (PMID 33006362, 2020).
cancer (continued). "These earlier studies suggested that CLDN4 plays an important role in cancer metastasis." (PMID 32269215, 2020). "Claudin-4 (CLDN4) is a tight junction protein to maintain the cancer microenvironment." (PMID 33172177, 2020). "We used claudin-4 as an epithelial marker because it was defined in the xCell epithelial gene list, but also because of its recent use as an epithelial IHC marker in SWI/SNF-deficient carcinoma." (PMID 33355532, 2020). "CLDN4 was expressed on the cytoplasmic membrane in normal colonic epithelial and cancer cells." (PMID 30647838, 2018). "However, the role of claudin-4 in the regulation of cancer-related cell functions, such as invasion and metastasis, remains controversial." (PMID 26109060, 2015). "Claudin-4 is the most frequently deregulated claudins in some cancers." (PMID 26109060, 2015). "For this reason, CLDN4 has been proposed as a target molecule for cancer therapy." (PMID 24586698, 2014). "Thus, an alteration in claudin-4 expression appears to play a role in the invasiveness of cancer cells, by modulating the barrier function of tight junctions or by mediating MMP-2 and -9 activity." (PMID 25120725, 2014). "In addition, Claudin-4 expression in undifferentiated or poorly differentiated carcinomas is lower than in well-differentiated counterparts." (PMID 25417118, 2014). "The exact role of claudin-4 overexpression and the functional importance of claudin-4 in the development of cancer remain unclear." (PMID 23599806, 2013). "On the basis of these observations, claudin-4 may represent a useful biomarker for detection and diagnosis of certain cancers." (PMID 23599806, 2013). "However, claudin overexpression, particularly that of claudin-3 and claudin-4, has been reported in various cancers." (PMID 24009024, 2013). "Moreover, we have also demonstrated that the recombinant fusion protein had significant anticancer ability in CLDN-4-positive cancer models in vivo." (PMID 22737166, 2012). "In addition, in vivo and in vitro data has revealed that over-expression of TJ proteins in cancer cells, such as Claudin-4, leads to a decrease in invasiveness and metastases in animal models." (PMID 22559840, 2012). "Furthermore, in 47% of sections of metastases, >50–100% of carcinoma cells stained positively for claudin-4." (PMID 18648369, 2008). "Therefore, CPE exhibits cytotoxicity against cancer cells expressing CLDN4." (PMID 36982569, 2023). "Therefore, Claudin-4 plays an important role in the occurrence and metastasis of cancer cells." (PMID 37465316, 2023). "Overexpression of CLDN4 is positively associated with the expression of metalloproteinase-2 (MMP-2) and metalloproteinase-9 (MMP-9), both of which exhibit the ability to degrade components of the extracellular matrix and eventually reinforce the invasive capacity and motility of cancer cells." (PMID 28819095, 2017). "Therefore, the preparation of an effective claudin-4 binder may help to reveal new pharmacological strategies to improve drug delivery, cancer treatment and mucosal vaccine development." (PMID 29109448, 2017). "Because these receptors are highly differentially expressed in many human tumors, claudin-3 and claudin-4 may provide an efficient molecular tool to specifically identify and target biologically aggressive human cancer cells for CPE-specific binding and cytolysis." (PMID 25835384, 2015). "In addition, the clinical implications of claudin-4 over-expression in various cancers and the molecular mechanisms leading to its dysregulation have remained largely unknown." (PMID 26109060, 2015). "CLDN4, a tight junction protein belonging to the CLDN family, has emerged as a potential biomarker for malignant tumors." (PMID 40487255, 2025). "CLDN4 and ELF3 expression was testified in all clusters and statistically significant increased expression of them were observed in cancer cell clusters C2, C5, and C7, indicating the similar expression status discovered in total cells." (PMID 38629624, 2024).